IL1B (interleukin 1 beta)
Diseases named in the same sentence as IL1B in open-access papers (continued):
Sharing a sentence is not in itself a finding about the gene and the disease.
tumor (continued). "The inflammatory microenvironment formed by inflammatory factors such as IL-1β, TNF-α, and IL-6 can promote the proliferation and interstitial transformation of tumor cells, thereby inducing their invasion and metastasis to adjacent or distant tissues." (PMID 40606986, 2025). "It induces chronic inflammation via cytokines such as IL-1β, IL-6, and TNF-α, fostering tumor progression." (PMID 39941737, 2025). "The precise interplay between AIM2 and IL-1β in NPC, particularly how they synergize to inhibit tumor progression, warrants further investigation." (PMID 40386782, 2025). "TAM-secreted cytokines such as IL-1β, IL-8, TNF-α, and TGF-β promote EMT in cancer cells, leading to disrupted intercellular junctions and accelerated tumor cell movement." (PMID 41417432, 2025). "Significant differences in expression were observed for TNF-α, TGF-β, IL-1α, IL-1β, and IL-12 between PeIN and early (I + II) and advanced-stage (III + IV) tumours (Kruskal–Wallis test, p < 0.05)." (PMID 41465261, 2025). "This initiates pyroptosis with concurrent release of ATP, HMGB1, interleukin-1β (IL-1β), and interferon-γ (IFN-γ), enhancing tumor immunogenicity and reversing immunosuppressive TIME." (PMID 40717985, 2025). "Key mediators such as IL-1β and TNF-α act as endogenous tumor promoters, driving angiogenesis, invasion, and metastasis." (PMID 41302515, 2025). "Tumor cell-derived prostaglandin E2 (PGE2) and tumor necrosis factor induce TAMs to secrete IL-1β, which in turn enhances PGE2 production and tumor necrosis factor in cancer cells, perpetuating a pro-inflammatory state." (PMID 40861469, 2025). "NLRP3 does so by enhancing IL-1β level, which, in turn, mediates the EMT and develops a pro-inflammatory environment that promotes tumor progression." (PMID 39941895, 2025). "M2-type macrophages promote tumor cell angiogenesis through a variety of mechanisms, including the secretion of factors such as VEGF, IL-1β, and TGF-β1." (PMID 40034694, 2025). "M1‐polarized macrophages are known to secrete high levels of IL‐1β and TNF‐α, which exert antiproliferative effects and can effectively kill tumor cells." (PMID 41306557, 2025). "The differentially expressed cytokines between tumor-bearing and tumor-free mice included CSF2, TGFB1, IL33, IL1B, and EGF." (PMID 41214328, 2025). "Tumor cells induce inflammation by activating white blood cells and releasing inflammatory cytokines (e.g., TNF-α, IL-1β, IL-6, IL-21, and TGF-β), which are critical at the tumor site." (PMID 41153842, 2025). "These conditions can promote pro-inflammatory cytokine release (IL-1β, IL-6 and TNF-α), angiogenesis and tumor proliferation." (PMID 41395614, 2025). "IL-1β and IL-6, regulated by JAK/STAT and NF-κB signaling, promote tumor proliferation and immune evasion, while IL-10 and TGF-β drive M2 macrophage polarization and Treg expansion, fostering an immunosuppressive tumor milieu." (PMID 40076502, 2025). "The nebulized NLU showed better anti-tumor, anti-inflammatory, and anti-oxidative effects than oral nintedanib in terms of LDH, CEA, AFP, MDA, TNF-α, and IL-1β." (PMID 41625777, 2025). "Various tumor-derived factors induce differentiation of MDSCs in vitro, including PGE2, IL-6, IL-10, IL-1β, TGF-β, stem cell factor (SCF), and proangiogenic VEGF." (PMID 40940764, 2025). "Tumor‐related angiogenesis is inhibited if either IL‐1β or VEGF are neutralized, as IL‐1β and VEGF can work as an auto‐induction circuit and interact with bone marrow–derived VEGFR1+/IL‐1R1+ immature myeloid cells (MDSCs) and tissue‐resident endothelial cells." (PMID 40135589, 2025). "Antibodies against CCR2, CSF1R, and IL-1β reduce TAM recruitment, survival, and polarization, improving the immunosuppressive tumor microenvironment." (PMID 41394845, 2025).
tumor (continued). "NLRP3 activity is central to this relationship in multiple tumour types, due to its role in coupling inflammasome activation to EMT via IL-1β–dependent signalling that engages NF-κB, TGF-β/Smad, and Wnt/β-catenin pathways." (PMID 41148809, 2025). "Neutrophils produce pro-inflammatory cytokines, such as IL-1β and TNF-α, which can enhance tumor cell proliferation and survival." (PMID 41180630, 2025). "During this immune activation period, the release of pro-inflammatory factors such as IL-1β and TNF-α can promote the migration of monocytes, neutrophils, and platelets, enhancing the action of immune cells against the tumor." (PMID 41440517, 2025). "In clear cell renal cell carcinoma, IL-1β+ and IL-18+ Tregs co-localize with MRC1+FOLR2+ TAMs at tumor-normal interfaces, forming a positive feedback loop that sustains synergistic pro-tumor effects." (PMID 41417432, 2025). "Numerous cytokines and chemokines such as IL-6, IL-1β, G-CSF, M-CSF, GM-CSF, macrophage migration inhibitory factor (MIF), and TGF-1 were present in the TME which attract MDSCs accumulation at tumor sites." (PMID 40141437, 2025). "In CAR-T therapy, granzyme B cleaves GSDME in tumor cells, which triggers macrophage activation of caspase-1/GSDMD and leads to IL-1β/IL-6 release." (PMID 41291696, 2025). "Key microglia-associated genes, including TREM2 and CX3CR1, regulate immune suppression, tumor proliferation, and invasion, while IL-1β and TNF-α contribute to tumor-promoting inflammation." (PMID 40076502, 2025). "Within the tumor microenvironment, cathepsin C activates membrane-bound PR3 on neutrophils, facilitating the processing of IL-1β and NF-κB activation." (PMID 41303697, 2025). "Cytokines such as VEGF, IL‐1β, PDGF, and FGF promote tumor formation, and IFNs, IL‐2, IL‐12, and IL‐15 inhibit tumor growth." (PMID 40356340, 2025). "In syngeneic murine colorectal (MC38) and prostate (RM-9) tumor models, RT activated the cGAS and AIM2 DNA-sensing pathways, leading to IL-1β upregulation and CXCL chemokine-mediated neutrophil recruitment." (PMID 40805288, 2025). "Macrophages and neutrophils in the tumor microenvironment shape a cytokine milieu (IL-6, IL-1β, TNF, CXCL8) that supports tumor growth and metastasis and counteracts antitumor immunity." (PMID 41440484, 2025). "Its activation triggers the release of inflammatory cytokines, such as IL-1β and IL-18, enhances CD8+ T cell infiltration, and improves chemosensitivity, thereby exerting potent tumor-suppressive effects." (PMID 40568597, 2025). "Chemokines and cytokines such as CSF2, CCL12, CCL20, IL1B, and CXCL3/5/6 are significantly upregulated in the tumor microenvironment, indicating that the body is extensively recruiting and activating myeloid immune cells." (PMID 41415031, 2025). "In both genotypes (WT and KO) and treatment groups (Veh and Bc), CD163+ Toe-Macs were detected within tumor regions expressing high levels of NLRP3, IL-1β, TGF-β1, CCL2, IL-6, and PD-L1." (PMID 40794443, 2025). "IL-1β inhibits osteoblast recruitment and suppresses osteoblast differentiation via the MAPK and NF-κB pathways while promoting tumor-induced bone metastasis." (PMID 40873591, 2025). "Cancer, especially advanced cancer, further amplifies this inflammatory milieu: tumours secrete cytokines (such as IL-1β, IL-6, and TNF-α) as part of immune evasion and tumour progression processes." (PMID 41149069, 2025). "They secrete pro-inflammatory cytokines and chemokines, including TNF-α, IL-1β, and CCL18, which facilitate tumor cell proliferation, angiogenesis, and metastasis." (PMID 41280929, 2025). "For instance, IL-1β and TNF-α signaling through NF-κB can lead to the expression of pro-inflammatory genes that promote tumor cell apoptosis." (PMID 40486614, 2025). "Responders exhibit a dominant signature characterized by IL1B, MIF, CXCL5, and HMGB1—indicating an inflamed, neutrophil-rich tumor microenvironment (TME) that is primed for antitumor immunity." (PMID 40723289, 2025).
tumor (continued). "The results showed that inhibiting macrophage-derived TNF-α and IL-1β decreased the growth of tumor cells and SPP1-NC also exhibited the secretion of TNF-α and IL-1β." (PMID 39726047, 2024). "Among the downregulated DEGs, four genes (LAMA1, ASPRV1, IL1B, PRR4) displayed reduced expression, while two genes (CCDC157, RP1) showcased elevated expression in tumor compared to normal tissue, respectively." (PMID 39062832, 2024). "We further define a glutamate-dependent neuron-oligodendrocyte interaction that results in IL-1β-mediated TAM production of Ccl5 production and tumor formation." (PMID 38308315, 2024). "The immune genes CXCL1, CXCL2, IL1B, IL6, CXCL8, PTGS2, and SPP1 demonstrated elevated expression levels in tumor tissue (TU) relative to all other tissues, thus validating the results obtained from the NanoString analysis (Supplementary 1)." (PMID 38979413, 2024). "Both in vitro and in vivo experiments and the use of VGX-1027, an inhibitor of macrophage-derived TNF-α and IL-1β, confirmed that SPP1 + Mac-derived TNF-α and IL-1β promoted HNSCC progression by supporting tumor cell proliferation and migration." (PMID 39726047, 2024). "The presence of IL-1β can induce NETosis, while the formation of NETs can trigger TGF-β-dependent EMT and resistance to chemotherapy in tumor cells." (PMID 39143953, 2024). "The summary of signaling pathway shows that ADAM17 activation is associated with many signaling pathways, such as inflammation response (e.g. IL-6, IL-1β, TNF, and TGF-β1), migration of tumor cells, tissue wound, and extracellular matrix organization." (PMID 38341954, 2024). "On the other hand, no statistically significant but slightly decreased profile of both caspase-1 and IL-1β in contact with PTX before and after NLRP3 knock-down demonstrated the ability of PTX to stimulate tumor cell death." (PMID 39433537, 2024). "Melatonin treatment and NLRP3 knockdown significantly inhibit tumor growth and downregulate NLRP3 and IL-1β expression in tumor tissues." (PMID 39230586, 2024). "At present, significant effort has been placed into the study of the anti-tumor therapeutic mechanism of several cytokines, such as IL-2, IL-12, IL-15, IL-24, IFN-γ, IL-1β, TNF-α, GM-CSF, and others." (PMID 38534538, 2024). "Pyroptosis also impacts the tumor microenvironment in HCC, with cytokines such as IL-1β and IL-18 playing roles in regulating immune responses." (PMID 39544286, 2024). "The requirement of IFN-γ and TNF-⍺/IL-1β for the upregulation of NOS2 and COX2 in human tumor cells implies that the microenvironment inducing NOS2-rich regions requires cells present that are releasing IFN-γ and other proinflammatory cytokines." (PMID 38892290, 2024). "XN demonstrates a dual anti-cancer effect by effectively suppressing NF-κB activity and IL1β expression in MCF7 cells and endothelial cells, impacting both tumor cells and angiogenesis." (PMID 38611849, 2024). "Treatment strategies that were the most effective in tumor destruction, namely NT GSDMD combined with IL-1β, IL-18, or IL-12, showed similar tissue characteristics." (PMID 39737979, 2024). "AIM2 displayed antitumor activity in tumor cells, and within HCC cells, the expression of Caspase‐1 and the concentrations of IL‐1β and IL‐18 were positively correlated with AIM2 expression." (PMID 39222064, 2024). "The high levels of ROS produced by mitochondrial dysfunction can stimulate tumor cells to release TNF-α, IL-6, and IL-1β, which attract suppressive immune cells and directly damage effector immune cells, reducing their activity." (PMID 39130746, 2024). "In present study, compared with tumor model group, the expression of NLRP3, caspase 1, GSDMD and the level of IL-1β and IL-18 in XRZYBXD high dose group were increased." (PMID 40046008, 2024). "The lower concentrations of pro-inflammatory cytokines IL-1β and IL-6 in SAADKO tumor-bearing mice suggest a diminished inflammatory response, which is consistent with findings from our previous CAC study." (PMID 39336082, 2024).
tumor (continued). "In clinical samples analysed by TCGA, the expression of 5 genes, CCL20, IL1B, IL24, PLAU and SEMA7A, was significantly higher in the primary tumour than in solid normal tissue, whereas that of CITED2 was lower." (PMID 38363001, 2024). "A study in which the authors analyzed the expression of IL-1β (among other 50 factors) in OSCC patients before and after surgical intervention showed a significant decrease in salivary IL-1β levels after tumor resection." (PMID 38473882, 2024). "Pro-inflammatory TAMs express TH1 response-inducing cytokines such as IL1α, IL1β, IL12 and TNFα while pro-tumor TAMs express IL10, CCL8, and CCL22 that are tumor promoting." (PMID 38802355, 2024). "On the other hand, Hp induces DNA methylation in two ways: directly, through the effect of its pathogenic product CagA protein, and indirectly, via chronic inflammation and the CpG-island methylation of tumor-suppressor genes such as CDH1, p16, and IL1β." (PMID 38542354, 2024). "M1 macrophages could produce inflammatory cytokines such as interleukin (IL)‐6 and IL‐1β, killing tumour cells and pathogenic microorganisms whereas M2 macrophages secret growth factors such as epidermal growth factor (EGF) participating in the tissue remodelling or tumour progression." (PMID 38680032, 2024). "Remarkably, the whole tumor transcriptome analysis revealed that IL-12 enriched pyroptosis and NT GSDMD + IL-1β + IL-18 treatments with different therapeutic outcomes exhibit enrichment in interferon signaling." (PMID 39737979, 2024). "CCL17 expression in M2 macrophages can activate Wnt/β-catenin signaling and promote EMT of tumor cells, while tumor cells in turn activate TAMs through the TLR4/TRIF/NF-κB signaling pathway and increase IL-1β production mediated by HIF1α to trigger EMT." (PMID 38957393, 2024). "The protein expression level of NLRP3, caspase 1, GSDMD, IL-1β and IL-18 in XRZYBXD high dose group were also significantly higher than those in the tumor model group by WB." (PMID 40046008, 2024). "Their activation leads to enhanced phagocytosis of tumor fragments and the release of proinflammatory cytokines like TNF-α and IL-1β." (PMID 39372411, 2024). "Tumor cells can release large amounts of pro-inflammatory cytokines, including TNF-α, IL-6, and IL-1β, into the bloodstream." (PMID 39697630, 2024). "The interleukin-1 beta (IL-1β) plays a significant role in CAF activation and leads to respective secretomes that favor tumor progression." (PMID 38468988, 2024). "When Salmonella damages cancer cells and bacterial components like flagellin and LPS are encountered, the macrophage inflammasome is activated, increasing IL-1β and TNF-α production in the tumor microenvironment." (PMID 39594765, 2024). "CAFs are a relevant cell population in the PDAC stroma that express IL-1R1, and when stimulated with IL-1α and/or IL-1β, they secrete several pro-tumor cytokines, including TSLP, which is responsible for pro-tumor Th2 inflammation in PDAC." (PMID 39125655, 2024). "Among these, IL-1B, IL-6, TNF, CXCLs, TGFB1, HMGB1, STAT3, and STAT5 have been reported to contribute to tumor formation." (PMID 39156107, 2024). "The lAPR and the IL‐1β, IL‐6, and COX‐2 induction can be considered as part of a self‐defensive reaction of tumor cells due to mEHT‐induced stress, although the role of the inflammation in cancer is not fully understood." (PMID 38217262, 2024). "Specifically, within the tumor microenvironment, Fg γ390-396A’s interaction with leukocyte integrin αMβ2 not only enhances the secretion of pro-inflammatory cytokines like IL-6, IL-1β, IFN-γ, and TNF-α but also promotes tumor cell proliferation." (PMID 38779081, 2024). "To that end we have shown that caspase-1-dependent IL1β production is a defining feature of TNBC that drives the recruitment of pro-tumoral TAMs, the exclusion of CD8+ T cells from the tumor core, tumor growth, and resistance to anti-PD1 immunotherapy." (PMID 39353903, 2024).
tumor (continued). "LINC01116 overexpression in the tumor recruited DDX5 to the interleukin-1β (IL-1β) promoter, increased IL-1β expression, and subsequently enhanced TAN recruitment." (PMID 39061147, 2024). "EVs originating from tumor cells often contain pro-inflammatory cytokines and chemokines, including TNF-α, IL-6, and IL-1β." (PMID 38802952, 2024). "On the other hand, the optimal induction of NOS2 and COX2 in murine and human tumor cells requires IFNγ, and its combination with TNF-⍺ and IL-1β was more effective than with LPS." (PMID 38892290, 2024). "The activation of macrophages in response to M1 stimuli, like TLR ligands, IL-1β, or TNF-α, as well as the transcription of various tumor-promoting genes, including VEGF, IL-6, and COX2, is primarily regulated by NF-κB." (PMID 39003350, 2024). "We stained tissue sections of the tumor-normal interface from 15 ccRCC patients for CD68, IL-1b, VEGFA and tryptase and analyzed the proximity of each MC4 cell to the nearest IL-1β+ macrophage and other macrophages." (PMID 39840068, 2024). "For instance, IL-1β has been identified as an important trigger of OC ascitic vascular endothelial growth factor (VEGF) production, a key protein involved in tumour angiogenesis." (PMID 39516433, 2024). "MDSCs also express FGF-2, PDGF, IL-1β, IL-28/IFN-λ, TGFβ, EGF, and HGF that can stimulate EC proliferation and migration, contributing to tumor angiogenesis." (PMID 38580870, 2024). "The significant tumor mass increase occurred in response to protumor cellular events, such as fewer CD3+ cells and signaling changes, such as higher IL‐1β levels and lower levels of IL‐12p70, IL‐23 and IFN‐β, in the TME." (PMID 38600057, 2024). "Briefly, SPP1 + Mac-derived TNF-α and IL-1β promote the expression of OPN in both macrophages and tumor cells." (PMID 39726047, 2024). "Our findings unveiled a significant upregulation in a variety of cytokines in UPP1-overexpressing tumor cells, including TGF-β1, GM-CSF, IL-1β, IL-6, IGFBP-3, CXCL5, CCL20, and VEGF, with TGF-β1 being the most prominently elevated." (PMID 38331898, 2024). "Pyroptosis induced by caspase-4/GSDMD can also promote the release of inflammatory factors such as IL-1β and IL-18, as well as recruit CD8+ T cell infiltration, thereby activating anti-tumor immunity." (PMID 39062587, 2024). "When using UALCAN to examine CK expression in HNSCC from the TCGA database, it is evident that IL-1β, IL-10, and TNF are highly expressed in tumor tissues with statistical significance (P < 0.01)." (PMID 38920620, 2024). "Trajectory analysis showed that IL-1β+ TAM originates from circulating monocytes and are induced by prostaglandin E2 (PGE2) secreted by tumour cells in PDAC patients and mice." (PMID 39430099, 2024). "In vitro and in vivo studies illustrated that IL-1β is a key mediator of IL-6 induction via activation of the NF-κB pathway, subsequently activating the IL-6/JAK/STAT3 cascade and promoting tumor growth and aggressiveness." (PMID 38103126, 2024). "In contrast to TAMs exhibiting an M2, pro-tumoral phenotype, M1 TAMs are classically associated with playing an anti-tumor role by secreting factors known to inhibit tumor growth, such as TNF-α, IL-1β, IL-6, IL-8, IL-12, and IL-23." (PMID 38893093, 2024). "M1 TAMs promote inflammation by secreting cytokines such as IL-1β, inducible nitric oxide synthase (iNOS), and tumor necrosis factor-alpha (TNF-α), exerting anti-tumor effects across multiple cancers." (PMID 39531417, 2024). "Marimastat treatment significantly reduced proinflammatory cytokines (Il‐1β and Il‐6), ER stress markers (CHOP and Grp78), and tumor markers (CD31 and AFP)." (PMID 38558505, 2024). "NT5E (CD73), CSF ligands, CD274 (PDL1), IL1B, IL6, and IL10 transcripts were primarily found in the peri necrotic zone, whereas NOS2 (iNOS), TGFB2, and NOX1 expression is localized to cellular tumor regions." (PMID 39272914, 2024).